PIK3C2G (phosphatidylinositol-4-phosphate 3-kinase catalytic subunit type 2 gamma)
Description:
Generates phosphatidylinositol 3-phosphate (PtdIns3P) and phosphatidylinositol 3,4-bisphosphate (PtdIns(3,4)P2) that act as second messengers (By similarity). May play a role in SDF1A-stimulated chemotaxis (By similarity).
Synonyms: PI3K-C2-gamma; PI3K-C2GAMMA
Tractability: Small molecule: a high-quality ligand is known; it belongs to a druggable protein family. Antibody: UniProt places it where antibodies can reach, with medium confidence; its Gene Ontology location is reachable by antibodies, with medium confidence; the Human Protein Atlas places it where antibodies can reach. PROTAC: a small molecule that binds it is known.
Target class: Enzyme; Transferase
Gene: Protein-coding gene on chromosome 12 (18,242,960 to 18,648,416, forward strand). Ensembl gene ENSG00000139144.
Subcellular location: Membrane
Subcellular location (Human Protein Atlas): Plasma membrane; Centrosome
Pathways (Reactome):
Metabolism: Synthesis of PIPs at the Golgi membrane; Synthesis of PIPs at the plasma membrane
Gene Ontology:
Molecular function: 1-phosphatidylinositol-3-kinase activity; 1-phosphatidylinositol-4-phosphate 3-kinase activity; phosphatidylinositol kinase activity; kinase activity; phosphatidylinositol binding
Biological process: host-mediated perturbation of viral process; cell migration; phosphatidylinositol 3-kinase/protein kinase B signal transduction; phosphatidylinositol-3-phosphate biosynthetic process; phosphatidylinositol-mediated signaling; phosphatidylinositol phosphate biosynthetic process
Cellular component: cytosol; membrane; plasma membrane
Genetic constraint (gnomAD): Loss-of-function variants: 50 observed, 51.31 expected, observed/expected ratio (o/e) 0.97, 90% interval 0.78 to 1.23. The upper end of that interval is the gene's LOEUF score, 1.23, which puts it in group 5 of 6, group 1 being the genes least tolerant of losing a copy. Missense variants: 783 observed, 728.53 expected, observed/expected ratio (o/e) 1.07, 90% interval 1.01 to 1.14. Synonymous variants: 237 observed, 252.91 expected, observed/expected ratio (o/e) 0.94, 90% interval 0.84 to 1.04.
Homologues: Orthologues: chimpanzee PIK3C2G (98% identical), macaque PIK3C2G (96% identical), dog PIK3C2G (85% identical), rabbit PIK3C2G (81% identical), pig PIK3C2G (80% identical), rat Pik3c2g (72% identical), mouse Pik3c2g (50% identical), tropical clawed frog pik3c2g (41% identical), zebrafish pik3c2g (29% identical), Drosophila melanogaster Pi3K68D (25% identical), Caenorhabditis elegans piki-1 (17% identical), Drosophila melanogaster Pi3K92E (16% identical), and 1 more. Paralogues in human: PIK3C2B (34% identical), PIK3C2A (34% identical), PIK3CD (16% identical), PIK3CA (16% identical), PIK3CG (16% identical), PIK3CB (16% identical), PI4KA (13% identical), PIK3C3 (11% identical), PI4KB (9% identical).
Diseases named in the same sentence as PIK3C2G in open-access papers:
PIK3C2G is named in the same sentence as 36 diseases in open-access papers, as found by Europe PMC text mining. Sharing a sentence is not in itself a finding about the gene and the disease. The quoted sentences say what the papers report.
ovarian carcinoma (3 papers, 2021 to 2025). A malignant neoplasm originating from the surface ovarian epithelium. "Our regression analysis identified six genes significantly associated with ovarian cancer: PI3, TFAP2B, MUC7, PSMA2, PIK3C2G, and NME1." (PMID 41154754, 2025).
breast carcinoma (2 papers, 2022 to 2024). "Beyond these malignancies, targeting PI3K signaling, including PIK3C2G, has shown therapeutic promise in cancers such as hepatocellular carcinoma, breast cancer, and renal cell carcinoma." (PMID 39950101, 2024). "We demonstrate that MMV652103 potently inhibits the oncogenic PI4KB and PIK3C2G lipid kinases, is selectively cytotoxic to MCF7 and T47D estrogen receptor positive breast cancer cells and inhibits their ability to survive and migrate." (PMID 35651652, 2022).
colorectal cancer (2 papers, 2021 to 2024). A primary or metastatic malignant neoplasm that affects the colon or rectum. "In the case of colorectal cancer, low copy number variants in PIK3C2G resulted in an increased recurrence and poor survival." (PMID 33782397, 2021).
diabetes (2 papers, 2020 to 2021). "We found that phosphatidylinositol-4-phosphate 3-kinase catalytic subunit type 2 gamma (Pik3c2g), a gene of interest for diabetes-related traits, had tissue-specific local-eQTL in all three tissues that closely matched the subspecies inheritance at their specific genomic coordinates." (PMID 31961859, 2020).
hyperlipidemia (2 papers, 2011 to 2025). "We identified seven CNV regions that were associated significantly with hyperlipidemia and myocardial infarction in our patients through multistage analysis (P<0.001), at 1p21.3, 1q31.2 (CDC73), 1q42.2 (DISC1), 3p21.31 (CDCP1), 10q11.21 (RET) 12p12.3 (PIK3C2G) and 16q23.3 (CDH13), respectively." (PMID 22369086, 2011).
Hypertension (2 papers, 2017 to 2023). The presence of chronic increased pressure in the systemic arterial system. "Furthermore, PIK3C2G, FIBIN, CHRNA1, NPNT, MEOX1, and POU2F2 linked obesity and lung cancer, while PTPRQ, SSUH2, CILP2, CDH2, ABCA12, CPXM1, and L1CAM linked hypertension and lung cancer." (PMID 36685671, 2023).
lung adenocarcinoma (2 papers, 2019 to 2024). A carcinoma that arises from the lung and is characterized by the presence of malignant glandular epithelial cells. "PIK3C2G was identified as a significant prognostic marker in stage IIb and IIIa lung adenocarcinoma, with functional data supporting its therapeutic potential." (PMID 39950101, 2024). "Indicating that both PIK3C2G and LTK contribute to the metastatic potential of lung adenocarcinoma cells." (PMID 39950101, 2024). "These distinct effects suggest that PIK3C2G and LTK regulate different aspects of cell cycle progression, highlighting their unique roles in lung adenocarcinoma biology." (PMID 39950101, 2024). "In addition, factors previously identified to be specific markers of lung adenocarcinoma were upregulated, including PROM2, CLDN3, and TJP3, as were genes proposed to have potential diagnostic or prognostic value in human cancers, including MMP9, AGR2, SULF1, NHSL1, LGR5, MUC1, and PIK3C2G." (PMID 31434729, 2019). "Cells transfected with siRNAs targeting either PIK3C2G or LTK exhibited markedly reduced growth rates compared to the control group, suggesting that both genes could play important roles in supporting cell proliferation in lung adenocarcinoma." (PMID 39950101, 2024).
lung carcinoma (2 papers, 2023 to 2024). "In our present study, LTK knockdown was used as a positive control, providing a reliable reference for assessing its role in lung cancer progression and for comparative evaluation of PIK3C2G’s functional impact in A549 cells." (PMID 39950101, 2024).
pancreatic cancer (2 papers, 2015 to 2024). "In pancreatic cancer, rs11922130 and rs9861030 across gene PLCD1 and rs11044171 across PIK3C2G were associated with cancer risk (P < 0.001)." (PMID 25683757, 2015).
prostate carcinoma (2 papers, 2014 to 2020). A carcinoma that arises from epithelial cells of the prostate gland. "Of note was PI3K family members: PIK3C2G, PIK3CA, PIK3CB, PIK3R4, Mucin family members: MUC1, MUC4 and MUC6 and other prostate cancer associated genes such as SMAD4, SOX9 and SPOP7,9,40,41." (PMID 32796921, 2020). "METAP2-PIK3C2G in tumor T17 resulted in the seven-fold upregulation of in-frame PIK3C2G, while FARS2-BMP6 in tumor T9 may also be relevant since BMP6 is linked to invasion of prostate cancer cells." (PMID 25155515, 2014).
schizophrenia (2 papers, 2008 to 2013). A major psychotic disorder characterized by abnormalities in the perception or expression of reality. "• SNPs in the gene PIK3C2G [phosphoinositide-3-kinase] have been shown to be associated with schizophrenia recently." (PMID 18837980, 2008). "The association identified in present study suggested evidence that areas of three genes (TBXAS1, PIK3C2G and HS3ST5) or related chromosome regions harbor susceptibility allele for schizophrenia with GM volume as QT." (PMID 24086445, 2013).
biliary tract cancer (1 paper, 2023). "Recent studies on the genomic characterization of biliary tract cancers have found commonalities of predisposing mutations, such as PI3KCA and PIK3C2G." (PMID 36978140, 2023).
Dandy-Walker syndrome (1 paper, 2019). "Of those subjects with available results, one had Dandy Walker Syndrome, one had Wiedemann Steiner Syndrome, one had a 15q13.3 microdeletion, one had 21q22.2 deletion, and one had MEF2C and PIK3C2G gene variants." (PMID 31780970, 2019).
glioma (1 paper, 2022). A benign or malignant brain and spinal cord tumor that arises from glial cells (astrocytes, oligodendrocytes, ependymal cells). "Genes from the RTK/PI3K pathway, including PTEN, PIK3R1 in glioma, and ALK, PIK3C2G, ERBB4 in melanoma, showed lower mutation rates in AYAs, reiterating our earlier observation on recurrent genes." (PMID 36433963, 2022).
granulosa cell tumor (1 paper, 2021). A slow-growing, malignant tumor, characterize by the presence of granulosa-like cells and Call-Exner bodies, that is almost always found in the ovary. "Although predicted deleterious variants in PIK3C2G, BMP5, and LRP2 were found, we could not identify an overlapping genetic variant or affected locus that may explain a genetic predisposition for granulosa cell tumors." (PMID 34069790, 2021).
hereditary cancer (1 paper, 2021). Malignant neoplasms occurring in families at a rate greater than that expected by chance and caused by germline mutations in a specific gene. "In addition, nonsense variants in apoptosis-related genes TP53AIP1, BCLAF1, and PIK3C2G were identified in our cohort; highlighting the potential relevance of genes involved in apoptotic processes to hereditary cancer." (PMID 33782397, 2021).
intrahepatic cholangiocellular carcinoma (1 paper, 2019). "Mutations in the PIK3C2G gene were significantly associated with poor prognosis in patients with intrahepatic cholangiocellular carcinoma (ICC)." (PMID 30884740, 2019).
lymph node metastasis (1 paper, 2021). "In contrast, patients without lymph node metastasis were found to have more frequent mutation in four genes including GATA3, FOXA1, ANKRD11, and RET (P<0.05) and more CN amplifications in two genes including PIK3C2G and CCND2 (P<0.05)." (PMID 33968723, 2021).
cancer (15 papers, 2015 to 2025). A tumor composed of atypical neoplastic, often pleomorphic cells that invade other tissues. "Other genes that showed potential association with cancer pain in HNSCC patients included PIK3C2G (rs10770367, p value = 1.10 × 10−3), TCRA (rs6572493, p value = 2.84 × 10−3), PDGFC (rs6845322, p value = 4.88 × 10−3), and CD247 (rs2995082, p value = 7.79 × 10-3)." (PMID 26872611, 2016). "Recent studies have begun to elucidate the unique roles of class II PI3Ks in cancer; for instance, PIK3C2A has been implicated in sustaining mitogenic signaling and cell division, while PIK3C2G is linked to cytoskeletal reorganization and membrane trafficking." (PMID 41362647, 2025). "PIK3C2G is involved in cell signaling pathways that regulate cell proliferation, survival, and oncogenic transformation, and is altered in 0.58% of all cancers." (PMID 34069790, 2021). "Mutations of PIK3C2G, PRKDC and DMBT1 are also commonly found in cancer patients." (PMID 36038950, 2022). "Besides alterations in these cancer hallmark genes, SNVs were identified in the less characterized genes GRM3, MST1R, PRKN, and PIK3C2G." (PMID 34399808, 2021). "Beyond metabolic disorder, PIK3C2G has also been found altered in different types of cancer." (PMID 30884740, 2019). "Although PIK3C2G has been implicated in cancer development, the specific genetic variation PIK3C2G rs10770367, to our knowledge, had not been associated with any health risk prior to this study." (PMID 26872611, 2016). "In conclusion, not only could PIK3C2G be an important biomarker in metabolic disorders like diabetes, due to its role in controlling cell metabolism at early endosome, it could also be used as a biomarker in specific types of cancer for recurrence and survival." (PMID 30884740, 2019). "Additionally, there was focal amplification on chromosome 12, involving PIK3C2G, a member of the class II PI3K kinase family, whose dysregulation may be involved in human metabolic diseases but its role in cancer remains unclear." (PMID 34925233, 2021). "Most of these genes, such as CDIPT, PIK3C2G, ARSJ, ARSE, GLA and GLB2, had not been studied in cancers." (PMID 31475440, 2019).
tumor (9 papers, 2014 to 2024). "The panel NGS of the primary tumor revealed pathogenic mutations in PBRM1 and PTEN and likely pathogenic mutations in VHL as well as PIK3C2G." (PMID 38611655, 2024). "PIK3C2G is an isoform of class II PI3Ks and a tumor suppressor." (PMID 33782397, 2021). "While PIK3CA mutations are strongly associated with lymph node metastasis and increased tumor invasiveness, PIK3C2G, another key PI3K family member, has emerged as a potential tumor suppressor." (PMID 39950101, 2024). "Evidence suggests that PIK3C2G and its related gene PIK3CG contribute to tumor progression and metastasis." (PMID 39950101, 2024). "Deletion of the PIK3C2G gene in the KPC pancreatic cancer mouse model initiated and promoted tumor development, explaining why low PI3K-C2γ expression is associated with poor survival and chemoresistance." (PMID 30338239, 2018). "Candidate pathogenic mutations in untranslated regions (UTRs) and BC-relevant genes regions, including oncogenes (i.e., KRAS, ERBB3, PIK3C2G) and tumor suppressor genes (i.e., FANCC, ATR, SMAD2), were found in organoids, and the majority of them were conserved within the tumor–organoid pair." (PMID 33371412, 2020). "According to theresults in our studied cohort, this gene behaves in a tumor suppressive mannerrather than oncogenic, which is uncommon with other genes of the PI3K family,but PIK3C2G has not been functionally characterized to the bestof our knowledge." (PMID 32799763, 2020).
PIK3C2G also shares sentences with these, for which no sentence is quoted: metabolic disorders (3 papers); adenoma (2); hepatocellular carcinoma (2); Obesity (2); dyslipidemia (1); ependymoma (1); Insulin resistance (1); melanoma (1); myocardial infarction (1); pericardial effusion (1); periodontitis (1); renal cell carcinoma (1); testicular tumors (1); triple-negative breast carcinoma (1); urothelial carcinoma (1); Wiedemann-Steiner syndrome (1).